RPLP2 (ribosomal protein lateral stalk subunit P2)
Diseases named in the same sentence as RPLP2 in open-access papers (continued):
Sharing a sentence is not in itself a finding about the gene and the disease.
infection (8 papers, 2013 to 2025). The state of being infected such as from the introduction of a foreign agent such as serum, vaccine, antigenic substance or organism. "Flaviviruses require RPLP2 for infection, because it is necessary for viral translation." (PMID 29700338, 2018).
tumor (8 papers, 2022 to 2025). "After transplanting RPLP2 knockdown Hep3B cells subcutaneously into nude mice, we found that tumor size and weight were obviously decreased upon the silencing of RPLP2." (PMID 37980521, 2023). "Immunohistochemistry analysis revealed a significant reduction in Ki67 expression levels in the tumours formed by sh-RPLP2 HCC cells." (PMID 38052785, 2023). "Here, we discovered RPLP2 knockdown significantly suppressed the proliferation, migration and colony formation of HCC cells via in vitro experiments, and xenograft nude mice model further proved that tumor growth was inhibited after knockdown of RPLP2." (PMID 37980521, 2023). "And the ROC curve analysis demonstrated that RPLP2 had great performance (AUC = 0.906) in distinguishing HCC tumor from normal control." (PMID 37980521, 2023). "In this study, we identified RPLP2 as a tumour autocrine factor that is highly expressed in HCC and promotes glycolysis in HCC cells, thereby facilitating cell proliferation both in vivo and in vitro." (PMID 38052785, 2023). "In this study, we identified a novel tumour autocrine molecule, RPLP2, which exerts regulatory control over the Warburg effect in HCC cells." (PMID 38052785, 2023). "Together, RPLP2 is overexpressed and exhibits a remarkable pro-tumor effect in DLBCL." (PMID 40564039, 2025). "For example, previous studies indicate that RPLP2 deficiency leads to stress-induced autophagy of gynecological tumors, and RPLP2 could facilitate HCC tumor growth by regulating glycolysis through the activation of the PI3K/AKT/HIF-1α pathway." (PMID 40564039, 2025). "Moreover, the IHC test also demonstrated that RPLP2 had higher expression level in DLBCL tissues compared to para-tumor tissues." (PMID 40564039, 2025). "Combined with the role of RPLP2 in ferroptosis of HCC cells, these results suggest that RPLP2 could promote cell proliferation and tumor growth of HCC by inhibiting ferroptosis." (PMID 37980521, 2023). "Most importantly, RPLP2 positively associates with ferroptosis suppressor GPX4, and inhibition of RPLP2 could lead to the acceleration of ferroptosis to suppress tumor progression of HCC." (PMID 37980521, 2023). "In addition, we revealed that RPLP2 plays a pro-tumor role in the progression of DLBCL." (PMID 40564039, 2025). "Moreover, our results showed that Destruxin b could suppress DLBCL tumor growth by targeting RPLP2, and the co-treatment of Destruxin b with Dox further improves the anti-tumor effect of Dox." (PMID 40564039, 2025). "Previous studies have demonstrated that RPLP2 functions as a pattern-associated molecular pattern (PAMP) that extracellularly binds to TLR4 on dendritic cell surfaces, thereby inducing dendritic cell maturation and activation in a TLR4-dependent manner and ultimately exerting tumour-immune effects." (PMID 38052785, 2023). "Generally, our present study revealed that high expression of RPLP2 is an independent adverse prognostic factor in HCC, and is significantly correlated with aggressive clinical characteristics, tumor growth and inhibition of ferroptosis." (PMID 37980521, 2023). "Previous study indicated that recombinant RPLP2 with Toll-like receptor 4 (TLR4) could induce the maturation and activation of DCs, and pulse tumor-specific antigen, to induce the activation of tumor-specific CD8IFN-γ T cells followed by tumor clearance." (PMID 37980521, 2023).
gynecologic tumors (5 papers, 2016 to 2025). "Considering the accumulation of ROS caused by the inhibition of RPLP2 in gynecologic tumors, and the significant effect of RPLP2 on ferroptosis-related pathway showed by GSEA in AML, we further investigated whether RPLP2 had an effect on ferroptosis of HCC cells." (PMID 37980521, 2023). "Recent studies indicate that RPLP2 deletion significantly correlates with ROS accumulation in gynecological tumors and induces ferroptosis mediated by GPX4 in HCC." (PMID 40564039, 2025). "The deletion of RPLP2 has been shown to induce autophagy in gynecological tumors and promote the ferroptosis of HCC cells." (PMID 40564039, 2025). "Ribosomal P protein (RPLP0, RPLP1, RPLP2) expression was previously shown to correlate with invasiveness and metastasis in gynecologic tumors." (PMID 27741504, 2016). "Studies have demonstrated that the silencing of RPLP2 could lead to the accumulation of ROS in gynecological tumor, and RPLP2 has an obvious effect on the critical ferroptosis-related pathway “Oxidative Phosphorylation” in AML showed by GSEA analysis." (PMID 37980521, 2023). "Additionally, it has been reported that the deletion of RPLP2 could lead to the abnormal accumulation of ROS in gynecological tumors, and promotes ferroptosis in HCC cells." (PMID 40564039, 2025).
RPLP2 also shares sentences with these, for which no sentence is quoted: glioblastoma (2 papers); acute myeloid leukemia (1); amyotrophic lateral sclerosis (1); benign breast tumours (1); bipolar disorder (1); digestive system tumors (1); escherichia coli infection (1); glioma (1); Hepatitis (1); jejunal cancer (1); lung adenocarcinoma (1); nephritis (1); osteoporosis (1); pancreatic cancer (1); prostate carcinoma (1); rheumatoid arthritis (1); Salmonella Infections (1); schizophrenia (1).